TRABD (TraB domain containing)
Description:
Along with MFN2, MIGA2 and PLD6 promotes mitochondrial clustering and fusion. May play a role in mitochondrial import of proteins, such as that of SLC25A19.
Synonyms: PP2447; LP6054
Tractability: PROTAC: ubiquitination databases record sites on it; its protein half-life has been measured.
Gene: Protein-coding gene on chromosome 22 (50,184,717 to 50,199,600, forward strand). Ensembl gene ENSG00000170638.
Subcellular location: Mitochondrion outer membrane
Subcellular location (Human Protein Atlas): Mitochondria; Nucleoplasm
Gene Ontology:
Molecular function: mitochondrion-mitochondrion outer membrane tether activity; protein binding
Biological process: mitochondrial fusion; protein localization to mitochondrion
Cellular component: mitochondrial outer membrane; mitochondrion; TOM complex
Genetic constraint (gnomAD): Loss-of-function variants: 27 observed, 40.06 expected, observed/expected ratio (o/e) 0.67, 90% interval 0.5 to 0.93. The upper end of that interval is the gene's LOEUF score, 0.93, which puts it in group 3 of 6, group 1 being the genes least tolerant of losing a copy. Missense variants: 487 observed, 536.31 expected, observed/expected ratio (o/e) 0.91, 90% interval 0.84 to 0.98. Synonymous variants: 243 observed, 224.49 expected, observed/expected ratio (o/e) 1.08, 90% interval 0.97 to 1.2.
Homologues: Orthologues: chimpanzee TRABD (99% identical), macaque TRABD (99% identical), mouse Trabd (93% identical), rat Trabd (93% identical), guinea pig TRABD (90% identical), pig TRABD (90% identical), dog TRABD (80% identical), zebrafish trabd (63% identical), Drosophila melanogaster CG46280 (41% identical), Caenorhabditis elegans F38A5.2 (39% identical).
Diseases named in the same sentence as TRABD in open-access papers:
TRABD is named in the same sentence as 5 diseases in open-access papers, as found by Europe PMC text mining. Sharing a sentence is not in itself a finding about the gene and the disease. The quoted sentences say what the papers report.
head and neck squamous cell carcinoma (1 paper, 2018). A squamous cell carcinoma that arises from any of the following anatomic sites: lip and oral cavity, nasal cavity, paranasal sinuses, pharynx, larynx, and salivary glands. "For example, we found a TRABD–DDR2 fusion in one head and neck squamous cell carcinoma (HNSC) sample, which fused the stronger TRABD promoter with DDR2, resulting in its overexpression." (PMID 29617662, 2018).
triple-negative breast carcinoma (1 paper, 2021). An invasive breast carcinoma which is negative for expression of estrogen receptor (ER), progesterone receptor (PR), and human epidermal growth factor receptor 2 (HER2). "The elevated HLA-F-AS1 expression induced by STAT3 promoted cell growth and stemness characteristics via sponging with miR-541-3p to upregulate the expression of a TraB domain (TRABD) containing triple-negative breast cancer cells." (PMID 34068010, 2021).
cancer (2 papers, 2022 to 2023). A tumor composed of atypical neoplastic, often pleomorphic cells that invade other tissues. "Compared with paracancerous tissues, AKAP7, EFEMP1, EPN2 and LAMA2 were lowly expressed in cancer tissues, while RPS6KA1, SLC1A6, TRABD and ZNRD1 were highly expressed in cancer tissues." (PMID 37123010, 2023). "Generally, HLA-F-AS1 is upregulated in cancers and affects the expression of cancer-related genes, such as PFN1 and TRABD, to promote tumor metastasis and growth." (PMID 35603775, 2022).
tumor (2 papers, 2020 to 2022). "It has been previously reported that latent EBV induces DNA hypermethylation, and that EBV-mediated silencing of tumor suppressor genes, such as IHH and TRABD, favors tumor proliferation." (PMID 32841292, 2020).
TRABD also shares sentences with these, for which no sentence is quoted: bladder cancer (1 paper).